ITCH (itchy E3 ubiquitin protein ligase)
Diseases named in the same sentence as ITCH in open-access papers (continued):
Sharing a sentence is not in itself a finding about the gene and the disease.
infection (8 papers, 2019 to 2024). The state of being infected such as from the introduction of a foreign agent such as serum, vaccine, antigenic substance or organism. "To test the effect of ITCH on the egress of native SARS-CoV-2 and the cytopathic effect (CPE) induced by SARS-CoV-2, we infected vT2-WT and vT2-ITCH-KO cells with SARS-CoV-2 at various multiplicities of infection (MOI)." (PMID 39677672, 2024). "After infection with ITCH-OE plasmids, the expression of ITCH protein significantly increased compared with that of NC, and the expression of ITCH mRNA increased, too." (PMID 37760946, 2023). "During infection, we observe a significant reduction in the expression of the E3 ubiquitin ligase, ITCH." (PMID 35658060, 2022). "At 24 h post infection, cells silenced for ITCH and infected with MOPV-ZF expressed higher amounts of intracellular Z protein than cells silenced with a non-targeting si-RNA and infected by the same virus." (PMID 31906112, 2019). "Eventually, both pathways contribute to parasite restriction in the host cells, highlighting the novel role of E3 ubiquitin ligase ITCH in mediating effector-triggered immunity and acting as a sentinel against pathogen infection across host species and cell types." (PMID 38376248, 2024). "Besides, gene-specific knockdown of Prmt5 in mouse peritoneal macrophages alleviated Mtb-mediated repression of ITCH during infection." (PMID 35658060, 2022). "While ITCH could interact with MOPV Z protein during infection, as shown by the slight quantity of ITCH co-immunoprecipitated with the Z protein in si-CTL cells, ubiquitinated Z protein could not be detected in the FLAG precipitates, in contrast with the previous observations in transfected cells." (PMID 31906112, 2019). "Finally, we assessed the impact of ITCH depletion on MOPV Z ubiquitination during infection." (PMID 31906112, 2019). "As many RNA viruses are already known to recruit proteins from the Nedd4 family, including ITCH, to facilitate budding, we investigated the role of ITCH, WWP1 and its homolog WWP2 during infection by various old-world arenaviruses." (PMID 31906112, 2019). "Consequently, siRNA-mediated depletion of YY1 or PRMT5 rescued ITCH expression, thereby compromising the levels of Mtb-induced ADRP and CD36 and limiting FM formation during infection." (PMID 35658060, 2022). "We determined the functional relevance of ITCH and WWP1 to old-world arenavirus infection by investigating the effect of siRNA-mediated depletion of these proteins during infection by four old-world arenaviruses, including three that are pathogenic (LCMV, LASV, LUJV) and one that is not (MOPV)." (PMID 31906112, 2019). "However, the HBcAg-negative area in past infection tissues showed strong ITCH and NUMB accumulation, suggesting that the E3 pathway was negatively correlated with HBV infection and Notch activity." (PMID 30733490, 2019). "Gene silencing showed that downregulation of A20, TAX1BP1, ABIN1, and ITCH but not RNF11, increased apoptosis in cells infected with HRSV at later times post-infection." (PMID 32102364, 2020).
cardiac diseases (2 papers, 2020 to 2022). "Among the nine members of the NEDD4 family, NEDD4-1, NEDD4L, ITCH, WWP1, WWP2, SMURF1 and SMURF2 are involved in heart diseases." (PMID 33110392, 2020).
adenocarcinoma (1 paper, 2019). A common cancer characterized by the presence of malignant glandular cells. "A total of 72 h after transfection of the siRNA, human adenocarcinoma alveolar basal epithelial (A549) cells were efficiently depleted for ITCH, WWP1 or WWP2, as compared to cells transfected with a non-targeting (NT) control siRNA." (PMID 31906112, 2019).
ITCH also shares sentences with these, for which no sentence is quoted: lymph node metastasis (3 papers); bladder (2); cardiovascular diseases (2); esophageal cancer (2); acute promyelocytic leukemia (1); bacterial infection (1); Barth syndrome (1); Bloom syndrome (1); Cohen syndrome (1); developmental delay (1); dilated cardiomyopathy (1); FILS syndrome (1); hyperlipidemia (1); Hypertension (1); ICF syndrome (1); idiopathic pulmonary fibrosis (1); Insulin resistance (1); invasive ductal carcinoma (1); Kabuki syndrome (1); metastatic disease (1); nephritis (1); non-small cell lung carcinoma (1); Obesity (1); oesophageal cancer (1); ovarian endometriosis (1); primary immunodeficiency (1); prolidase deficiency (1); renal fibrosis (1); sarcoma (1); skin pigmentation disorder (1).
A further 4 diseases each share a sentence with ITCH in 1 paper.